HOXA9 (homeobox A9)
Diseases named in the same sentence as HOXA9 in open-access papers (continued):
Sharing a sentence is not in itself a finding about the gene and the disease.
squamous cell lung carcinoma (3 papers, 2011 to 2025). A carcinoma arising from squamous bronchial epithelial cells. "In squamous cell lung cancer, hypermethylation in genes SOX1 (p = 0.05) and HOXA9 (p = 0.01) is more frequent than in other histological types of NSCLC." (PMID 40699796, 2025).
atherosclerosis (2 papers, 2020). A disease characterized by the build-up of fatty material and calcium deposition in the arterial wall resulting in partial or complete occlusion of the arterial lumen. "For example, HoxA9, HoxA10, and HoxD3 were expressed at higher levels in EC isolated from iliac arteries that are relatively protected from atherosclerosis compared to coronary arteries that are atherosusceptible." (PMID 31504243, 2020). "Although HOXA9 is linked to the susceptibility to atherosclerosis 22, HOXA9 did not change YAP‐5SA‐induced 8×GTIIC‐luciferase activity (Fig EV3B) or CTGF expression (Fig EV3C)." (PMID 32147946, 2020).
chordoma (2 papers, 2017 to 2023). Chordomas are rare malignant tumors arising from embryonic remnants of the notochord in axial skeleton. "Comparison of chordoma with NP showed DMRs in many cancer-related genes as well as in genomic cluster encoding homeobox domain genes (at HOXD3, HOXD4 and HOX11, HOXA9, HOXA10) that play an important role in both normal differentiation and tumorigenesis." (PMID 37434245, 2023).
clubfoot (2 papers, 2024 to 2025). The most common congenital deformation of the foot, occurring in 1 of 1,000 live births. "Initially, genes associatedwith clubfoot (PITX1, TBX4, HOXA9, HOXD10, HOXD12,HOXD13, HOXA9, TPM1, TPM2, COL9A1, FLNB, CASP8,CASP10, UTX, CHD1, RIPPLY2, CAND2, WNT7) werescreened for potential variants." (PMID 38952703, 2024). "Furthermore, an SNP within the HOXA9 gene in conjunction with CASP10 has implications in apoptosis among simplex clubfoot cases." (PMID 40746736, 2025). "Moreover, an investigation into an SNP in HOXA9 uncovered specific interactions with nuclear proteins and increased promoter activity, suggesting that alterations in the HOXA9 promoter region can impact gene expression, thus influencing the functional aspects of the isolated etiology of clubfoot." (PMID 40746736, 2025).
colon adenocarcinoma (2 papers, 2024). "Interestingly, contrary to miR-140-3p, HOXA9 exhibited upregulation in colon adenocarcinoma (COAD) and rectum adenocarcinoma (READ) tumor tissues." (PMID 38285101, 2024).
colorectal adenocarcinoma (2 papers, 2022). The most common type of colorectal carcinoma. "The expression of HOXA9 was significantly upregulated in colorectal adenocarcinoma tissues (p < 0.01)." (PMID 35176937, 2022). "This study was carried out to investigate the function of PCED1B-AS1 in regulating the microRNA(miR)-633/HOXA9 axis in colorectal adenocarcinoma." (PMID 35176937, 2022). "Our results demonstrated that knockdown of PCED1B-AS1 inhibited the progression of colorectal adenocarcinoma by regulating the miR-633/HOXA9 axis." (PMID 35176937, 2022). "In addition, overexpression of HOXA9 obviously attenuated the protective role of knockdown of PCED1B-AS1 or miR-633 mimics in colorectal adenocarcinoma progression." (PMID 35176937, 2022). "In summary, our study revealed that PCED1B-AS1 promotes the proliferation of colorectal adenocarcinoma through regulating the miR-633/HOXA9 axis, suggesting that PCED1B-AS1 might be considered as a potential therapeutic target for colorectal adenocarcinoma." (PMID 35176937, 2022). "Moreover, overexpression of HOXA9 obviously attenuated the inhibitory effect of miR-633 mimics in colorectal adenocarcinoma progression." (PMID 35176937, 2022). "We found that HOXA9 was a target of miR-633 and rescue experiments revealed that HOXA9 mediated the role of PCED1B-AS1 and miR-633 in the progression of colorectal adenocarcinoma." (PMID 35176937, 2022). "In this study, we aimed to investigate the role of PCED1B-AS1 in colorectal adenocarcinoma tissues and to identify the potential relationship among PCED1B-AS1, miR-633 and HOXA9 in colorectal adenocarcinoma." (PMID 35176937, 2022).
endometrial cancer (2 papers, 2020 to 2025). Primary or metastatic malignant neoplasm involving the endometrium (mucous membrane that lines the endometrial cavity). "Global methylation analysis of Hoxa9 expression in endometrial cancer tissues and healthy tissues revealed that Hoxa9 was hypermethylated in cancer tissues and it was associated with lymphovascular tumor invasion." (PMID 33402862, 2020). "Moreover, hypermethylation of Hoxa9 was also shown in DNA samples isolated from the vaginal tampon of endometrial cancer patients." (PMID 33402862, 2020).
esophageal squamous cell carcinoma (2 papers, 2020 to 2022). Esophageal squamous cell carcinoma (ESCC) is a type of esophageal carcinoma (EC) that can affect any part of the esophagus, but is usually located in the upper or middle third. "For instance, it was found that HOXA7 and HOXA9 mRNAs were elevated in esophageal squamous cell carcinoma tissues." (PMID 35349479, 2022).
metastatic disease (2 papers, 2021 to 2022). "CRC candidates, HOXB8, FOSL1, and HOXA9, were commonly and specifically associated with SEs in all chemoresistant and metastatic tumor samples." (PMID 34432948, 2021). "A total of 28 patients (72%) had metastatic disease and meth-HOXA9 was detectable in 37 patients (95%)." (PMID 36230519, 2022).
myopia (2 papers, 2019 to 2023). "Among 8 pre-school children with SE less than -2D, 7 had hypomethylation at HOXA9 which suggested that over-expressed HOXA9 could be a risk factor for early onset myopia." (PMID 30674274, 2019). "HOXA9 can transcriptionally activate transforming growth factor-β (TGF-β) and TGF-β signaling has long been implied as a risk factor for myopia." (PMID 30674274, 2019). "In the present study, we investigated the effects of HOXA9 on myopia using human, animal and cellular samples." (PMID 30674274, 2019). "The expression levels of myopia-related genes and cell proliferation were measured in the HOXA9-overexpressed RPE cells." (PMID 30674274, 2019). "Although our findings are intriguing, more studies are needed to confirm the role of HOXA9 in myopia development." (PMID 30674274, 2019). "The HOXA9 expression levels were measured in the eyes of mono-ocular form deprivation myopia in mice." (PMID 30674274, 2019). "Although we show molecular evidence to support HOXA9 as a novel myopia gene, it is warranted that future studies use more animal and human data to validate the role of HOXA9 in myopia." (PMID 30674274, 2019). "The mouse primary RPE cells were further used to test for the role of over-expressed HOXA9 in myopia development." (PMID 30674274, 2019). "HOXA9 may encourage pro-myopia gene expression and RPE growth, which ultimately aid in the development of myopia." (PMID 37740201, 2023). "In addition, our methylation profiles of genomic DNA showed aberrant methylation at HOXA9 in myopia of preschool children (see details in the Result section)." (PMID 30674274, 2019). "We demonstrated that over-expression of HOXA9 in RPE cells could increase pro-myopia substances including TGF-β, FGF2, IGF1R and MMP2." (PMID 30674274, 2019). "Since HOXA9 is a transcription factor, it may directly or indirectly affect expression of pro-myopia genes." (PMID 30674274, 2019). "However, we acknowledge that our initial discovery of HOXA9 in relation to myopia development was based on small samples of human subjects and animals." (PMID 30674274, 2019). "Our data is the first to suggest that HOXA9 may affect myopia development via multiple mechanisms including myopia-related genes and RPE proliferation." (PMID 30674274, 2019). "We have shown that over-expression of miR-328 is a risk for myopia and PAX6 may have a link with HOXA9, and therefore we tested whether miR-328 can affect HOXA9 expression in both human and mouse RPE cells." (PMID 30674274, 2019). "In addition, it has been noted that HOXA9 activates TGF, a risk factor for myopia." (PMID 37740201, 2023). "In addition, HOXA9 also increases cell proliferation, which may facilitate eyeball elongation during myopia development." (PMID 30674274, 2019). "Therefore, we tested whether alteration of HOXA9 expression can affect these potential myopia markers." (PMID 30674274, 2019). "Our data implied that HOXA9 may play a role in myopia development." (PMID 30674274, 2019). "Based on the human, animal and cellular data, the transcription factor HOXA9 may promote the expression of pro-myopia genes and RPE proliferation, which eventually contribute to myopia development." (PMID 30674274, 2019).
nasopharyngeal carcinoma (2 papers, 2022 to 2024). A carcinoma arising from the nasopharyngeal epithelium. "In nasopharyngeal carcinoma, HOXA9 was associated with advanced clinical and T stage." (PMID 39462379, 2024). "In addition, the function of HOXA9 in Nasopharyngeal carcinoma (NPC) is also explored." (PMID 36376832, 2022).
oral squamous cell carcinoma (2 papers, 2017 to 2021). "In oral squamous cell carcinoma (OSCC), miR-139-5p inhibited tumorigenesis by targeting HOXA9 and CXCR4." (PMID 34576110, 2021).
ovarian serous cancer (2 papers, 2020 to 2024). "In addition, HOXA9 mRNA expression in high grade ovarian serous cancer was associated with a low survival rate." (PMID 39462379, 2024).
pancreatic ductal adenocarcinoma (2 papers, 2022 to 2024). An infiltrating adenocarcinoma that arises from the epithelial cells of the pancreas. "The role of HOXA9 requires investigations in pancreatic ductal adenocarcinoma (PDAC) as HOXA9 inhibitors are being developed." (PMID 39462379, 2024). "Several genes in the 500 kb vicinity of HOXA5 (i.e., HOXA3, HOXA9, HOXA7, HOXA1, EVX1) were also associated with high density lipoprotein (HDL) cholesterol efflux capacity, BMI, and pancreatic ductal adenocarcinoma." (PMID 35836279, 2022).
prostate tumors (2 papers, 2020 to 2022). "TWIST1 functioning as a transcription factor co-expressed with HOXA9 was activated in prostate tumors, research further showed that TWIST1, WDR5 and the lncRNA HOTTIP formed a complex and regulated the chromatin in the promoter of HOXA9." (PMID 36376832, 2022).
thyroid cancer (2 papers, 2019 to 2020). "However, there have been no reports regarding the role of HOXA9 in thyroid carcinoma." (PMID 31043660, 2019).
adenoma (1 paper, 2008). A neoplasm arising from the epithelium. "ADAMTS1, CDKN2A, CRABP1, MLH1, NR3C1, RUNX3, and SCGB3A1 showed increasing methylation frequencies from adenomas to carcinomas, while HOXA9, MAL, and MGMT displayed overall equal methylation frequencies in all tumor subgroups." (PMID 19117505, 2008).
anencephaly (1 paper, 2019). A rare neural tube defect during pregnancy, resulting in the absence of a large portion of the brain and skull in the fetus. "To investigate the potential effect of expression levels of the selected HOX genes (HOXA1, HOXA7, HOXA9, HOXA10, HOXB1, and HOXB7) in anencephaly, we evaluated 10 anencephaly cranial tissues and 10 matched normal fetus cranial samples by the NanoString technique." (PMID 30992047, 2019).
biliary tract cancer (1 paper, 2022). "The aim of this retrospective study was to investigate the clinical impact of the circulating tumor DNA (ctDNA), methylated homeobox A9, in plasma from 39 patients receiving erlotinib and bevacizumab for non-resectable biliary tract cancer." (PMID 36230519, 2022).
chromophobe renal cell carcinoma (1 paper, 2017). Chromophobe renal cell carcinoma is a rare subtype of renal cell carcinoma, originating from the intercalating cells of the collecting ducts and macroscopically manifesting as a well-circumscribed, highly lobulated, solid tumor that is usually diagnosed at an early stage. "HOXA9 promoter methylation allowed for discrimination between oncocytoma and both papillary and chromophobe renal cell carcinoma but only with 77% sensitivity and 73% specificity." (PMID 28662726, 2017).
cystic kidneys (1 paper, 2018). "Additionally, in mice uniformly sacrificed at 2 months of age, 10–15% of the Hoxa9,10,11−/− Hoxc9,10,11+/−, and Hoxa9,10,11+/− Hoxc9,10,11−/−, and triple heterozygote Hoxa9,10,11+/− Hoxc9,10,11+/− Hoxd9,10,11+/− mice showed grossly cystic kidneys (X’, Y’)." (PMID 29679048, 2018).
hand-foot-genital syndrome (1 paper, 2012). Hand-foot-genital syndrome (HFGS) is a very rare multiple congenital abnormality syndrome characterized by distal limb malformations and urogenital defects. "While it is known that mutations in HOXA13 or HOXD13 can cause specific limb phenotypes, such as hand-foot-genital-syndrome or synpolydactyly, no HOXA9-related disease phenotype has been identified in patients so far, leaving the role of HOXA9 during human limb development unclear." (PMID 23028966, 2012).
leukocytosis (1 paper, 2024). "The cKO+Hoxa9 group also had greater leukocytosis and more severe thrombocytopenia." (PMID 39004675, 2024).
lymph node metastasis (1 paper, 2024). "The results indicated that low miR-140-3p expression was associated with lymph node metastasis (p < 0.05), and high HOXA9 expression was associated with lymph node metastasis and lympho-vascular invasion (p < 0.05)." (PMID 38285101, 2024). "Reduced miR-140-3p expression was associated with lymph node metastasis, while high HOXA9 expression correlated with both lymph node metastasis and lympho-vascular invasion." (PMID 38285101, 2024). "Clinical data demonstrated that low miR-140-3p expression and high HOXA9 expression were associated with lymph node metastasis and poor prognosis in CRC patients." (PMID 38285101, 2024). "Our data showed miR-140-3p and HOXA9 predict the poor prognosis and indicated its expression related to clinical lymph node metastasis." (PMID 38285101, 2024).
lymphopenia (1 paper, 2015). Reduction in the number of lymphocytes. "Regardless, TS cells must be highly sensitive to the MZ developmental signal as mild lymphopenia, as we document in FL-/- and HoxA9-/- mice, is sufficient to promote the MZ B cell fate." (PMID 26029370, 2015).
metastatic cancer (1 paper, 2020). A carcinoma which has spread from the original site of growth to another anatomic site. "In primary or metastatic cancer, mRNAs IGF2BP3, HOXA9, HOXA10, CEBPG competed with HOXA11-AS mutually, and HOXA10 as well as IGF2BP3 were also continuously up-regulated among normal-primary-metastatic process with significant difference in variance analysis." (PMID 33614509, 2020).
MRKH syndrome (1 paper, 2023). "Several genes have been implicated in MRKH syndrome, such as HOXA7, HOXA9–13, HOXD9–13, and WNT4." (PMID 37240886, 2023).
Obesity (1 paper, 2022). Accumulation of substantial excess body fat. "This further included 10 identical annotations among the PAX6 and HOXA9‐10 gene clusters, already known candidates regarding obesity and related comorbidities." (PMID 35692099, 2022).
oncocytoma (1 paper, 2017). "Furthermore, in patients with low OXR1 and MST1R methylation level (NPV: 97%), HOXA9 methylation level distinguished oncocytoma from chRCC and pRCC." (PMID 28662726, 2017).
pituitary adenomas (1 paper, 2022). "The changes in pituitary adenomas after different treatments were further analyzed to verify the ceRNA mechanism of ST8SIA6-AS1/miR-5195-3p/HOXA9." (PMID 35783150, 2022). "This study is aimed at comparing the expression levels of ST8SIA6-AS1 and HOXA9 in invasive pituitary adenoma and noninvasive pituitary adenoma tissues." (PMID 35783150, 2022). "Results showed that HOXA9 expression was higher in invasive pituitary adenoma tissues than in noninvasive tissues." (PMID 35783150, 2022). "The expression levels of ST8SIA6-AS1 and HOXA9 in noninvasive pituitary adenoma and invasive pituitary adenoma were detected using qRT-PCR." (PMID 35783150, 2022). "The regulatory mechanism of HOXA9 expression must be elucidated to understand the pathogenesis of tumors, especially pituitary adenoma." (PMID 35783150, 2022). "The expression of HOXA9 in invasive pituitary adenoma and noninvasive pituitary adenoma was detected to measure the expression of HOXA9 in pituitary adenoma." (PMID 35783150, 2022). "ST8SIA6-AS1 and HOXA9 were highly expressed in invasive pituitary adenoma." (PMID 35783150, 2022). "ST8SIA6-AS1 targets miR-5195-3p to regulate the expression of HOXA9 and promote the EMT of pituitary adenomas." (PMID 35783150, 2022).
pituitary tumours (1 paper, 2015). "On this basis, we reasoned that the differences in methylation frequency observed for HOXA9 and ISL1 may be consequent to different clinical characteristics and/or outcomes within our HG tumour cohort; a phenomenon similarly described in, for example, breast, colon and pituitary tumours." (PMID 26332997, 2015).
renal agenesis (1 paper, 2018). Renal agenesis (RA) is a form of renal tract malformation characterized by the complete absence of development of one or both kidneys (unilateral RA or bilateral RA respectively), accompanied by absent ureter(s). "However, in mice with a single wild type copy of Hoxa11 present (Hoxa9,10−/−11+/− Hoxc9,10,11−/−), renal agenesis occurred in only 16% of mutants." (PMID 29679048, 2018).
sarcopenia (1 paper, 2024). Progressive decline in muscle mass due to aging which results in decreased functional capacity of muscles. "The overexpression of Hoxa9 (homeobox A9), one of the master regulators of embryonic development therefore limits satellite cell self-renewal and muscle regeneration in old mice, likely contributing to sarcopenia." (PMID 38339110, 2024).
serous carcinomas (1 paper, 2022). "The univariate and multivariate Cox regression analyses were repeated in the subgroup of patients with high-grade serous carcinomas, in which meth-HOXA9 remained significant of outcome." (PMID 35406538, 2022).
Splenomegaly (1 paper, 2024). Abnormal increased size of the spleen. "Survival was similar between Ctrl+Hoxa9 and cKO+Hoxa9 groups in primary recipients transplanted with multiple doses (400 K, 100 K, or 30 K cells), with similar degrees of leukemic infiltrate and splenomegaly at morbidity." (PMID 39004675, 2024).
T-cell acute lymphoblastic leukemia (1 paper, 2019). Acute lymphoblastic leukemia of T-cell origin. "In T-cell acute lymphoblastic leukemia (T-ALL), HOXA9 acts as an oncogene by cooperating with JAK3/STAT5 at the transcriptional level through upregulating the expression of downstream genes, such as PIM1 and activator protein-1 (AP-1), thereby affecting cell survival and apoptosis." (PMID 31013831, 2019).
thymoma (1 paper, 2020). A neoplasm arising from the epithelial cells of the thymus. "This analysis revealed that Meis1-3, Pbx1-3, and Hoxa9 genes are highly upregulated in thymoma when compared to healthy adult tissues." (PMID 33402862, 2020). "Publications about thymoma and the analysis of Meis1-3, Pbx1-3, or Hoxa9 expression in thymoma are limited." (PMID 33402862, 2020).
tongue cancer (1 paper, 2014). A malignant neoplasm affecting the tongue. "To investigate the possible functional significance of reduced expression of HOXA9, we re-expressed HOXA9 in SCC4 tongue cancer cells (SCC4-HOXA9), which resulted in diminished proliferation compared to control SCC4 cells with an empty vector construct (SCC4-empty vector)." (PMID 24886209, 2014).
triple-negative breast carcinoma (1 paper, 2021). An invasive breast carcinoma which is negative for expression of estrogen receptor (ER), progesterone receptor (PR), and human epidermal growth factor receptor 2 (HER2). "Numerous studies have reported that lncRNAs play a critical role in different cancers. lncRNA MIR503HG inhibits cell proliferation and promotes apoptosis in triple-negative breast cancer (TNBC) cells via the miR-224-5p/HOXA9 axis." (PMID 34141458, 2021).